BDNF (brain derived neurotrophic factor)
Diseases named in the same sentence as BDNF in open-access papers (continued):
Sharing a sentence is not in itself a finding about the gene and the disease.
alcohol dependence (55 papers, 2008 to 2026). Physical and psychological dependence on alcohol. "BDNF has been implicated in the identification of neurocognitive function in individuals with alcohol dependence." (PMID 39126094, 2024). "Further studies should continue to investigate other typologies of alcohol-dependence, such as Type B alcoholism, which is often associated with family history of alcoholism and related genetic data (BDNF gene)." (PMID 36873223, 2023). "A correlation was revealed between the risk of alcoholism development and Val68−>Met68 polymorphism in the BDNF gene in mice." (PMID 32231011, 2020). "As a chronic disease state, alcohol dependence is associated with neurological illness.Through binding with the TrkB receptor, BDNF activates the MAPK signaling pathway, whichplays a major role in alcohol addiction." (PMID 26108098, 2015). "The Val66Metpolymorphism in the BDNF gene is associated with an earlier occurrenceof alcohol dependence and a higher risk of relapse." (PMID 26108098, 2015). "It would be interesting to expand upon these results and determine if a link exists between stress-associated changes in DNMT3a and methylation of the BDNF gene and alcoholism." (PMID 23584115, 2012). "Moreover, miR-206 was previously found to contribute to alcohol dependence by reducing BDNF mRNA production, a crucial molecule implicated in plastic changes associated with memory and learning." (PMID 38334898, 2024). "In addition, clinical and preclinical studies demonstrate an association between increased BDNF serum levels and alcohol dependence." (PMID 38535622, 2024). "In addition, this study revealed a BDNF-centered gene network associated with alcohol dependence and other related phenotypes." (PMID 36551763, 2022). "However, data on the interactive effects of early life adversity, genetic factors (e.g. p.Met66 allele of BDNF), and alcohol dependence, on brain structure in adolescents is limited." (PMID 25510982, 2014). "Aberrant regulation of BDNF signaling and alterations in synapse activity (i.e., synaptic plasticity) have been associated with the pathophysiology of stress-related disorders and alcoholism." (PMID 23584115, 2012). "Thus, the decreased levels of BDNF and IGF-1 in patients with AUD that we observed are in accord with other studies in alcohol, which have reported an association between decreased BDNF levels and alcohol intoxication and between inhibited IGF-1 bioavailability and chronic alcohol abuse." (PMID 29108028, 2017). "Therefore, it may be important to study the potential regulation of amygdaloid BDNF by chromatin remodeling and its role in dysphoria associated with the development of alcoholism." (PMID 23584115, 2012). "In alcohol dependence, several clinical and preclinical studies reveal significant correlations between BDNF expression and drinking patterns, withdrawal severity, and risk of relapse." (PMID 40725591, 2025). "This study aimed to explore the role of BDNF gene variants, personality traits and impulsivity in both the presence of AUD and the age of onset of alcohol dependence." (PMID 40767639, 2025). "Strikingly, in the postmortem amygdala of patients with early onset alcohol dependence, brain-derived neurotrophic factor (BDNF)-antisense lncRNA is hypomethylated, leading to decreased expression levels of BNDF." (PMID 38674366, 2024). "Regarding the effect of Val66Met polymorphism of the BDNF gene on AUD, epidemiological studies have shown that BDNF gene Val66Met polymorphism increases vulnerability to alcohol dependence." (PMID 38721616, 2024). "More noticeable discoveries concerning the correlation between alcohol dependence and BDNF levels have been made through animal studies." (PMID 37845289, 2023). "Conduction of further studies investigating probable links between genes related to BDNF expression and alcohol dependence would be elucidative in this regard." (PMID 37845289, 2023).
alcohol dependence (continued). "The 80 coding genes discovered in the present GWAS are active in pathways ‘Alcoholism’ (one of the key genes is BDNF), ‘Dopaminergic synapse’, ‘Glutamatergic synapse’, and ‘Long-term potentiation’." (PMID 36551763, 2022). "It has been shown that the level of BDNF in patients with alcoholism was significantly lower than that in healthy volunteers." (PMID 34526917, 2021). "Another study in mouse observed a reduction in ethanol dependence after BDNF infusion in the pre-frontal cortex, evidencing that BDNF levels in specific brain areas play a role in alcohol dependence." (PMID 32760684, 2020). "It was found that alcoholism led to disbalance of pro-BDNF–p75NTR–sortilin and mature BDNF (mBDNF)–TrkB interactions." (PMID 32231011, 2020). "Alcohol abstinence has been reported to increase circulating BDNF levels in patients with alcohol dependence." (PMID 32679912, 2020). "Comparison of leptin, leptin/BMI, nesfatin-1, nesfatin-1/BMI, inflammatory cytokines, cortisol, and BDNF levels between alcohol-dependent patients and healthy controls after 1 month of abstinence." (PMID 32265847, 2020). "Here we report that the epitranscriptome and epigenetic mechanisms interact to regulate BDNF expression in the amygdala and are possibly involved in the pathophysiology of alcoholism that begins with drinking during adolescence." (PMID 30728347, 2019). "Compared to healthy controls, subjects with alcohol dependence have been found to have unchanged or decreased serum BDNF and unchanged, higher, or lower plasma BDNF." (PMID 29330839, 2018). "The lymphocyte mRNA levels of BDNF (t = −2.804, P = 0.01, Student’s t-test) and TrkB (t = 5.733, P < 0.001, Student’s t-test) were significantly reduced in the alcohol dependence group (n = 28) compared to the control group (n = 46)." (PMID 29520063, 2018). "We found the results that in alcohol dependence patients, the mRNA levels of BDNF and TrkB were downregulated which leading to the proteins they translated into changed in line." (PMID 29520063, 2018). "A number of studies have suggested that BDNF (mature BDNF) and its precursor (proBDNF) play important roles in the alcohol dependence." (PMID 29520063, 2018). "We remain interested in BDNF as an intermediate signaling molecule in the establishment of alcohol dependence, as we have displayed its involvement with opiate dependence." (PMID 29556175, 2018). "Rat models of alcoholism showed that augmenting BDNF actions by the use of the selective BDNF tyrosine kinase B receptor agonist (7,8-dihydroflavone) removed withdrawal-induced depression-like behavior." (PMID 28082989, 2016). "The purpose of this study was to investigate the relationship between cognitive functions and BDNF in alcohol-dependent patients." (PMID 26405456, 2015). "As a neurotrophin associated with the survival and development ofneurons, BDNF can regulate the activity of neurotransmitter systems.Compared with other neurotrophic factors, BDNF may be directly involved in thedevelopment and pathogenesis of alcohol dependence." (PMID 26108098, 2015). "This article reviews research that attempts to describe the role of epigenetic mechanisms in the regulation of BDNF function in alcoholism and stress." (PMID 23584115, 2012). "Studies regarding the epigenetic control of BDNF signaling and synaptic plasticity provide a promising direction to understand the mechanisms mediating the interaction between stress and alcoholism." (PMID 23584115, 2012). "The 5-HT system and BDNF are key regulators of neuroplasticity in alcoholism." (PMID 41594648, 2026). "Experimental data show that pharmacological or genetic restoration of BDNF expression mitigates dendritic spine loss, improves hippocampal plasticity and reduces alcohol intake in animal models, while alterations in circulating BDNF levels have been reported in patients with alcoholism." (PMID 41516173, 2025). "Studies found that BDNF and FGF21 are associated with alcohol dependence and impulsivity." (PMID 38721616, 2024).
alcohol dependence (continued). "In the context of alcohol intoxication, the upregulation of the lncRNA could ameliorate BDNF expression, in which BDNF-AS seems to be regulated by diminished levels of m6A." (PMID 38674366, 2024). "Moreover, offspring from families with multiple cases of alcohol dependence have a greater likelihood of developing AUD that is caused by an interaction between allelic variation in GABRA2 and BDNF genes." (PMID 38928583, 2024). "NGF and BDNF are peptides that not only play a pivotal role in the development, survival, and function of the central and peripheral nervous systems but also regulate the pathogenesis of other problems induced by alcohol exposure." (PMID 38539304, 2024). "Other previous studies have suggested that increased BDNF signalling may have a potential protective role in the development of alcohol dependence, and alcohol intake has been shown to reduce BDNF expression in rodents." (PMID 37372084, 2023). "It is assumed that epigenetic regulation of growth factors, such as glial cell line-derived neurotrophic factor (GDNF) and BDNF, may contribute to the development of alcohol dependence." (PMID 36834747, 2023). "Based on these findings, we hypothesized that taVNS could ameliorate PAWS in alcohol-dependent patients, the mechanism of which may be related to its regulation of plasma BDNF, IL-6, TNF-α, and leptin levels." (PMID 34526917, 2021). "Thus, people suffering from alcoholism tend to have a dysregulation of the balance between pro-BDNF/p75NTR/sortilin and mBDNF/TrkB." (PMID 32231011, 2020). "Furthermore, the p75NTR level was the opposite of those of BDNF and TrkB during alcohol dependence and abstinence." (PMID 29520063, 2018). "Brain-derivedneurotrophic factor (BDNF) and its receptors affect the pathogenesis of alcoholism.In this study, we examined the expression of BDNF, tropomyosin receptor kinase B(TrkB) and p75 neurotrophin receptor (p75NTR) in the hippocampus of a dog model ofchronic alcoholism and abstinence." (PMID 26108098, 2015). "The findings suggest that BDNF might serve as a biomarker mirroring neuroregenesis among patients with alcohol problems and as a protective factor against alcohol-induced neurodegeneration." (PMID 26405456, 2015). "BDNF might play an important role in the detection of neurocognitive function among individuals with alcohol dependence." (PMID 26405456, 2015). "Finally, the article will outline the potential role of the epigenetic control of BDNF signaling and synaptic plasticity in alcoholism and stress." (PMID 23584115, 2012). "However, another animal study suggests that BDNF Val66Met polymorphism dose not play a significant role in the genetic predisposition to alcohol dependence or violent tendencies." (PMID 38721616, 2024). "Likewise, dysregulated lncRNAs may be found in the brain of individuals with alcohol dependence; this dysregulation may contribute to the abnormal production of brain-derived neurotrophic growth factor (BDNF) in individuals with alcohol dependence." (PMID 38674366, 2024). "In addition to this, we should note that patients with a positive family history of alcohol dependence have a lower mean BDNF blood levels that may demonstrate the probable role of BDNF in the pathophysiology of alcohol dependence." (PMID 37845289, 2023). "Furthermore, analyses considering sociodemographic and clinical data demonstrated that the percentage of variation in BDNF levels was significantly lower for those who had a first-degree relative with alcohol dependence (14.8 [-5.3;35.6] vs. 35.3 [15.4;74.8]; p = 0.005,Table 1andFigure 1B)." (PMID 34060728, 2022). "Furthermore, the observed changes in serum BDNF may also play a role in the reported reduction of alcohol dependence." (PMID 32267550, 2020). "Our data pertaining to BDNF and IGF-1 support growth factors could be linked to alcohol dependence." (PMID 29108028, 2017).
alcohol dependence (continued). "We investigated the effects of BDNF rs6265 and FGF21 rs11665896 on impulsivity with alcohol dependence during withdrawal." (PMID 38721616, 2024). "In particular, voluntary wheel running increases neurotrophins, both BDNF and NGF, and NGF has been shown to be responsible for exercise-induced rescue of the cholinergic phenotype following alcohol-related brain damage." (PMID 39436939, 2024). "Finally, we analyzed the expression of the brain-derived neurotrophic factor (BDNF)- tropomyosin receptor kinase B receptor (Trk-B) system as BDNF regulates ethanol intake by activation of downstream gene products like pDYN and is known to have a role in alcohol dependence vulnerability." (PMID 33671048, 2021). "Lee33 found that plasma BDNF and NGF levels were higher in patients with alcohol dependence than in the healthy subjects." (PMID 29520063, 2018). "In the alcoholism group,pyramidal cells in the CA1, CA3 and CA4 regions were loosely arranged and reduced innumber, but in the few remaining BDNF-positive neurons, the cytoplasmic staining wasnoticeably darker, and the nucleus was clearly visible." (PMID 26108098, 2015). "These preclinical and clinical findings show that the role of BDNF in AUD remains unclear and could differ between different stages of alcohol use and different experimental models." (PMID 37372084, 2023). "The goal of this study was to evaluate the effect of transcutaneous auricular vagus nerve stimulation (taVNS) on PAWS and plasma brain-derived neurotrophic factor (BDNF), interleukin-6 (IL-6), tumor necrosis factor-α (TNF-α), and leptin levels in patients with alcohol dependency." (PMID 34526917, 2021). "Our findings suggest BDNF-TrkB in VTA is a part of regulating signals for opposing neural adaptations in AUD, and 7,8-DHF may serve as a potential candidate for treating alcoholism." (PMID 32508571, 2020). "Some reported no significant changes of BDNF serum level in alcohol dependence patients as compared with healthy controls." (PMID 29520063, 2018). "Compared with the control group, the number of BDNF-positive cells in thegranular cell layer of the DG and in the pyramidal cell layer of the CA1, CA3 and CA4regions were significantly decreased in the alcoholism group (P<0.05)." (PMID 26108098, 2015). "Patients with a family history of alcohol dependence showed lower BDNF levels than those without such a family history." (PMID 26405456, 2015). "The influence of BDNF and COMT on neurocognition in alcohol dependence is unclear." (PMID 23087644, 2012). "Moreover, individuals who had first-degree relative with alcohol dependence had smaller increases in BDNF levels than individuals with no family history (14.8 [95%CI -5.3; 35.6] vs. 35.3 [95%CI 15.4; 74.8]; p = 0.005)." (PMID 34060728, 2022). "The goal of this study was to determine whether the plasma leptin, nesfatin-1, cortisol, brain-derived neurotrophic factor (BDNF), and inflammatory cytokines could be used as potential biomarkers for the degree of craving in the alcohol-dependent patients after 1 month of abstinence." (PMID 32265847, 2020). "However, the results of BDNF expression in serum in the alcohol dependence were not consistent." (PMID 29520063, 2018).
autism spectrum disorder (55 papers, 2011 to 2026). A spectrum of developmental disorders that includes autism, and Asperger syndrome. "The fact that BDNF can restore defective synapse maturation in NL1-deficient neurons is important for therapeutic concepts addressing reduced maturation in autism spectrum disorders." (PMID 34579720, 2021). "Reduced BDNF in the neonatal period has been associated with increased risk of developing autism spectrum disorder whilst elevated BDNF in the weeks after preterm birth is associated with better cognitive performance in childhood." (PMID 34512648, 2021). "Nevertheless, elevated levels of CX3CR1 and BDNF in microglia were also associated with autism spectrum disorders." (PMID 32765258, 2020). "Notably, hypoplasia of vermal lobules VI-VII has been linked to autism spectrum disorder and is in part attributed to brain-derived neurotrophic factor (BDNF)/tropomyosin receptor kinase B signaling." (PMID 40538625, 2025). "The dysregulation of BDNF was linked with numerous NDDs such as Autism Spectrum Disorder (ASD, ICD-11 6A02), dyslexia (ICD-11 6A03) and intellectual disability (ICD-11 6A00) (Esnafoglu and Adıgüzel, 2021), but not with Attention Deficit Hyperactivity Disorder (ADHD, ICD-11 6A05)." (PMID 38523647, 2024). "Furthermore, BDNF levels in preterm neonates differ from BDNF levels in full-term neonates, thereby affecting cognitive development in early postnatal life and potentially being associated with children’s mental diseases such as autism spectrum disorders." (PMID 32944867, 2020). "To date, although several studies have investigated the circulating levels of brain-derived neurotrophic factor (BDNF) in children with autism spectrum disorder (ASD), only a few authors have addressed their evaluation in adults." (PMID 39062102, 2024). "The link of BDNF with oxytocin expands the possible mechanisms which are relevant to autism spectrum disorder, as well as other neuropsychiatric disorders." (PMID 35721318, 2022). "We have recently found significantly lower neonatal levels of BDNF in newborns later diagnosed with autism spectrum disorders." (PMID 34631615, 2021). "Brain-derived neurotrophic factor (BDNF), a key peptide in neurocognitive development, has been reported to be elevated in the serum of children with autism spectrum disorder (ASD)." (PMID 34518555, 2021). "In contrast, BDNF levels in children with autism spectrum disorder and Down syndrome are high compared with the general population." (PMID 29321033, 2018). "Recently, researchers have begun to explore the relationship between peripheral BDNF levels and autism spectrum disorder (ASD), but the findings are inconsistent." (PMID 27506602, 2016). "Conversely, BDNF is increased in autism spectrum disorders (ASD)." (PMID 24804781, 2014). "Various mechanisms, such as Toxoplasma infection, reduced levels of brain-derived neurotrophic factor (BDNF), early childhood adversity, and links with autism spectrum disorders, may account for some of this overlap." (PMID 25548672, 2014). "Conversely, autism spectrum disorders (ASDs) are characterized by an increase in BDNF level." (PMID 23320097, 2013). "Prenatal bisphenol A exposure induces persistent epigenetic alterations, as evidenced by validated BDNF promoter hypermethylation in neonatal PBMC, which correlates with the development of autism spectrum disorder." (PMID 40863927, 2025). "Another possibility, perhaps implied by increased serotonin associated with autism spectrum disorder and presumably with the rs4446909 G allele, is that a crucial effect of reduced ASMT expression is accumulation of N-acetylserotonin, which we now appreciate may influence the BDNF-TRKB interaction." (PMID 21827647, 2011). "BDNF knockout models promote similar ASD phenotypes characterized by stereotyped behaviors, social deficits, hyperplastic circuitry, and behavioral phenotypes evident in the autism spectrum disorder." (PMID 40362507, 2025).